IL22 (interleukin 22)
Diseases named in the same sentence as IL22 in open-access papers (continued):
Sharing a sentence is not in itself a finding about the gene and the disease.
colitis (continued). "FICZ provides protection against colitis by reducing the production of pro-inflammatory cytokines such as IL-17, IL-1β, IL-6, TNF-α, and IFN-γ, while promoting anti-inflammatory IL-22 production from Th17 cells." (PMID 39767818, 2024). "Collectively, intestinal colonization with C. tropicalis enhanced IL-17A/IL-22 expression, barrier function, and epithelial cell proliferation in the colon of mice with DSS-induced colitis." (PMID 39462273, 2024). "Together, this suggests a potential regulatory role of USP28 in modulating IL22 and IFNγ expression during acute DSS-induced colitis, with implications for the involvement of the IL2 pathway in this context." (PMID 39076972, 2024). "BTW regulated Trp metabolism to increase metabolite levels, activate the AHR/IL-22 pathway to restore intestinal barrier function, and significantly alleviated DSS-induced colitis." (PMID 38974042, 2024). "Deletion of SIRT6 in ILC3s resulted in increased IL-22 production and protected mice from C. rodentium infection and DSS-induced colitis." (PMID 39253083, 2024). "Further analyses performed in vivo and in vitro demonstrate that Akk stimulates IL-22 secretion from ILC3s by replenishing the population and RA synthesis activity of diminished CD103+ DCs in colitis mice, ultimately promoting mucosal healing." (PMID 39734222, 2024). "It is thus possible that the inflammatory response during colitis-induced FGF21 expression inhibits intestinal HIF1α expression, leading to a decrease in IL-22 and therefore exacerbating the expression of inflammatory IL-6 production." (PMID 37432218, 2023). "Using caspase-1/11-/-, NLRP3-/-, NLRC4-/-, IL18-/-, and IL22-/- mice, we showed that KLPJ-mediated colitis occurred through activation of caspase-11, and was dependent on IL18 and partly on IL22." (PMID 36436756, 2023). "A previous study has revealed a link between IL-22 and STAT3 signaling in intestinal epithelial renewal in DSS-induced colitis." (PMID 37114045, 2023). "Overall, this panel identified IL-6, IL-22, IL-13, LT-α and TNF-α as upregulated inflammatory markers and CD40L as a downregulated marker of DSS-induced experimental acute murine colitis." (PMID 36672648, 2023). "Together, these results demonstrated that B. fragilis promoted IL-22-mediated pSTAT3 phosphorylation to promote colonic mucosal proliferation and mucus secretion, and modulate intestinal microbiota in DSS-induced colitis." (PMID 37114045, 2023). "We identified polyfunctional mucosal CD4+ and CD8+ T cells that co-produce IFNγ, other pro-inflammatory cytokines (e.g. IL22, IL17A) and cytotoxic molecules, including granzyme B, as key effector cells in CPI colitis." (PMID 37872166, 2023). "Similar trends were observed for IL-22, IL-13, LT-α and TNF-α, with small increases measured within the 2% DSS group and significantly higher systemic levels when the colitis worsens within the 3–5% DSS groups." (PMID 36672648, 2023). "By contrast to what was herein observed with the acute model of colitis induced by DSS, higher numbers of epithelial apoptotic bodies and increased expression of TNF-α and IL-22 were observed in NOD2▵Lyz2 mice in a T cell-mediated model of ileopathy." (PMID 37876927, 2023). "With a larger degree of fold-induction in treated vs. control animals, our data indicate that IL-6, IL-22 and LT-α would be the most useful markers in a DSS-induced colitis model." (PMID 36672648, 2023). "Moreover, IL-22 increases intestinal barrier function and anti-microbial peptide production, and iNKT cells trigger ILC3s to produce IL-22 in the intestine, indicating that secretion of IL-22 by ILC3s following their interaction with iNKT cells might be effective in preventing colitis development." (PMID 38274786, 2023). "Lactobacillus reuteri can prevent DSS-induced colitis in mice via tryptophan metabolites such as indole 3-aldehyde, an AHR ligand that activates AHR and enhances IL-22 production." (PMID 37304260, 2023).
colitis (continued). "Recently, it has been shown that KD can reduce RORγt+CD3− Group 3 ILCs and the production of related inflammatory cytokines including IL-17α, IL-18, IL-22, and Ccl4 in DSS induced colitis, protecting intestinal barrier function." (PMID 37318214, 2023). "Other cytokines assessed were for the most part unchanged other than IL-6, IL-22, and KC (CXCL1) which were likewise increased in plasma of both C57BL/6 and TCRδ-/- mice with DSS colitis indicative of systemic inflammation." (PMID 37063825, 2023). "Anti-inflammatory cytokines (such as IL-4, IL-10, IL-22, etc.)can inhibit the proliferation of TH17 and TH2 cells and intestinal wall disorders, thus alleviating colitis in mice." (PMID 37240380, 2023). "Th17 cells produced IL-17 and IL-22 in the culture medium of colon cells, which were considerably upregulated by FimH compared to those of DSS-induced colitis." (PMID 38077339, 2023). "For organ-specific irAEs, IL-6 levels were higher in patients with thyroiditis and colitis, while IL-22 and SCF levels were higher in patients with colitis." (PMID 36159840, 2022). "During colitis with intact KLF5, IL-22 helps signal regeneration in the intestinal epithelium through p-STAT3 signaling." (PMID 35393949, 2022). "Both IL-22 and IL-6 activate STAT3 signaling, but epithelial STAT3 activation in DSS-induced colitis depends more on IL-22 than on IL-6." (PMID 36142515, 2022). "In this study, we discovered enhanced ISC regeneration and increased intestinal IL-22 secretion and its related transcription factor AHR in colitis mice after L-fucose treatment." (PMID 36432480, 2022). "As expected, colitis mice treated with Bp7 and Bp8 exhibited lower concentrations of TNF-α and IL-1β (p < 0.05) and higher concentrations of IL-10 and IL-22 relative to the DSS group (p < 0.05)." (PMID 35681301, 2022). "We have demonstrated the incredible role of bioactive compound, such as IL-22, in alleviating DSS-induced colitis symptoms via enhancing lncRNA-UCL expression." (PMID 36092152, 2022). "It has been shown that RA inhibits the induction of iNOS and COX-2 expression and production of pro-inflammatory cytokines such as IL-6, IL-22 and IL-1β in DSS (dextran sulphate sodium)-induced colitis in the mouse model." (PMID 35079027, 2022). "ILC3s were important with regard to maintaining the defence against C. rodentium, because Rag−/− mice on a D- diet presented lower levels of IL-22 from ILC3, and therefore had more severe colitis and a higher mortality than their D+ diet littermates." (PMID 34659248, 2021). "Microbiota: Microbiota-derived short-chain fatty acids (SCFAs) promoted IL-22 production by CD4+ T cells and ILC3s both in vitro and in vivo, resulting in a significant inhibition of C. rodentium-colitis." (PMID 34659248, 2021). "So, it seems that the microbes of IL-22–/– mice were transmitted to wildtype litter- and cage-mates, and in turn were able to influence the levels of antimicrobial peptides and DSS colitis severity in these wildtype mice." (PMID 34603258, 2021). "In comparison to IL-10 and IL-22, we observed that IL-6 was the most abundantly produced cytokine during DSS-induced colitis development in wild-type mice as well as in mice with reduced STAT3 activity." (PMID 33673239, 2021). "In line with this, PP cells from MSC-/- mice express much higher levels of IL-22 than MSC+/+ PP cells, and this difference is greatly amplified during colitis." (PMID 34992594, 2021). "IL-22 has also been shown to be protective in colitis, including the DSS-induced colitis model using IL-22 or the stabilized IL-22Fc fusion protein UTTR1147A used in the experiments described here, and is under clinical development in IBD." (PMID 34360971, 2021). "Recently, other members of the DOK family of proteins, namely DOK1 and DOK2, have been shown to regulate colitis severity through inhibiting the expression of Th17 cytokines IL17A and IL22 in DOK1/2 double knockout mice." (PMID 34743196, 2021).
colitis (continued). "Although this inverse expression was observed in a DSS-mediated model of colitis and mechanical injury in mice, IBD patients can have elevated levels of both IL-22 and IL-22BP." (PMID 34868019, 2021). "Others showed, using the exact same RORC inhibitor, that while IL-17A levels were reduced, the production of IL-22 continued and treatment with the RORC inhibitor abrogated experimental colitis." (PMID 34552583, 2021). "Further, haplodeficiency of RORγt with genetic ablation of AhR spontaneously induces colitis indicating the importance of RORγt in maintaining the ILC3 compartment and subsequent IL-22 production in tandem with AhR activation." (PMID 33777031, 2021). "Animal colitis models suggest that exaggerated ILC3 activation worsen experimental colitis through the secretion of IL-17A and IL-22 and subsequent excess neutrophil influx resulting in tissue damage." (PMID 34118489, 2021). "IL-22 reduced inflammation and intestinal cancer in the acute phase of DSS-induced colitis by fortifying the epithelial barrier function and limiting the microbial influx." (PMID 32376911, 2020). "IL-22 is secreted by various immune cells, but neutrophils, in particular, have been shown to secrete IL-22 in response to DSS-induced colitis." (PMID 33339337, 2020). "For example, E. coli flagellin enhances TLR5 signaling in intestinal DCs, leading to a higher expression of IL-22 and better maintenance of the intestinal barrier, to protect mice against DSS-induced colitis." (PMID 33381598, 2020). "Taken together, these findings suggest that C. muridarum upregulates IL-22 and occludin in mice with DSS-induced colitis." (PMID 33381598, 2020). "Similar to IL-10, IL-22 exerts a protective effect on mucosal inflammation in most animal models, but plays a harmful role in the anti-CD40-induced colitis model, which will be discussed later in this section." (PMID 32670290, 2020). "Mice given NPD-0414-2 and NPD-0414-24 developed a significantly less severe form of TNBS colitis following decreased expression of IFN-γ and increased expression of IL-22." (PMID 31772949, 2019). "TREM-1 increases IL-1β production by M1 macrophages during DSS-induced colonic inflammation and thereby influences ILC3-mediated IL-22 production." (PMID 31189465, 2019). "Collectively, our results showed that TP5 increases the output of lymphocytes, elevates the expression of IL-22, normalizes the composition of the gut microbiome, and thus, alleviates DSS-induced colitis." (PMID 31695782, 2019). "Mice given NPD-0414-2 and NPD-0414-24 developed a significantly less severe form of TNBS colitis and exhibited reduced expression of IFN-γ and increased expression of IL-22." (PMID 31031628, 2019). "Adding an AHR agonist rescued IL‐22 and adenosine monophosphate (AMP) production and protected from colitis in CARD9–/–, again showing the importance of AHR ligands in promoting IL‐22 production and epithelial barrier function." (PMID 31107965, 2019). "Our findings indicate that TREM-1 protects mice against acute DSS-induced colitis by promoting ILC3 activation and the production of IL-22 that restores epithelial barrier integrity." (PMID 31189465, 2019). "Infection with C. rodentium elicits robust tissue repair responses, which are characterized by production of IL-22 and cell proliferation leading to colonic crypt hyperplasia (CCH), as well as colitis." (PMID 30365535, 2018). "IAld induced AhR-dependent IL-22 production by ILC and mediated both antifungal activity and amelioration of chemically induced colitis." (PMID 29124320, 2018). "ILC3 are involved in clearance of bacterial and fungal infection, control of enteric virus infection, and maintenance of microbiota, while recent studies suggest that GM-CSF, as well as IL-22, expressed by ILC3 participate in ILC-driven colitis." (PMID 29354125, 2017). "In contrast, retinoic acid, a vitamin A metabolite, enhances IL-22 production by γδ T cells in vitro and inhibits DSS-induced colitis." (PMID 27298823, 2016).
colitis (continued). "Colitis induced by WT T cells is characterized by a multifunctional response with high amounts of IFN-γ and GM-CSF and a lower IL-17A and IL-22 response." (PMID 27193261, 2016). "Restoring microbial AhR-ligand biosynthesis ameliorates DSS colitis, presumably because indole derivatives stimulate AhR in immune cells predominantly Group 3 Innate Lymphoid Cells (ILC3) to release IL-22 or activate AhR in IEC, thereby directing differentiation and function of ISC." (PMID 41530817, 2026). "Mechanistically, inhibitor CH223191 markedly down-regulated the mRNA and protein levels of AhR and its downstream targets CYP1A1 and IL22 in colonic tissue compared with HQD treatment alone, underscoring the critical role of AhR activation in HQD-mediated alleviation of experimental colitis." (PMID 41530817, 2026). "ILC3-specific deficiency of nucleophosmin 1 (NPM1) in mice did not affect the number of ILC3s but resulted in decreased IL-22 production and exacerbated colitis." (PMID 40498001, 2025). "To further determine which TH17 cytokines are responsible for inhibiting chemokine expression and protect the Tak1ΔM/ΔM mice against colitis and CRC, we performed intracellular staining of key TH17 cytokines (IL-17A, IL-17F, IL-21, and IL-22) in CD4+ cells from intestinal LP." (PMID 40749055, 2025). "In addition, in a dextran sulfate sodium (DSS)-induced colitis mouse model, NTBF was shown to promote colonic mucosal regeneration by stimulating interleukin-22 (IL-22) production." (PMID 40559883, 2025). "On one hand, the lack of IL-22 exacerbates colitis and T cell-mediated colitis in adoptive transfer models, and is necessary for optimal host defense against pathogens." (PMID 40429917, 2025). "Our study demonstrated that the transcription levels of both IL-17 and IL-22 were suppressed by vitamin D, which may prevent the proinflammatory effects of the synergy between IL-17 and IL-22 in DSS colitis." (PMID 40563965, 2025). "Moreover, mice colonized with Lactobacillus reuteri D8 produce elevated levels of the metabolite indole-3-aldehyde, an AHR ligand, which enhances ILC3s-derived IL-22 production and attenuates DSS-colitis." (PMID 41194916, 2025). "In the same line, no alterations were found to IL-22 production in colonic explants at baseline and upon colitis induction." (PMID 39918275, 2025). "Our results demonstrated that the cecal gene expression of IL-6, CXCL2 (murine IL-8 homologue), IL-1β, TNF-α, IL-17a, IL-22, and CRAMP (homologue of human cathelicidin LL-37) was significantly elevated in the mice with P. aeruginosa-infected colitis after chemotherapy." (PMID 38397855, 2024). "Previously, we published results showing I3C treatment during colitis led to increased production of IL-22 specifically in ILC3s, not Th22, and this was important since neutralization of IL-22 negated I3C-mediated protective effects." (PMID 39229279, 2024). "The decreased production of IL-22 in ILC3s may contribute to the observed dysregulation of Reg3b and Reg3g in Npm1+/− mice in DSS-induced colitis, and thus impaired intestinal microbiota homeostasis." (PMID 39103576, 2024). "Depletion of AhR in IECs also did not impact the ability of I3C to enhance the production of IL-22 by ILC3s during colitis." (PMID 38397081, 2024). "We estimated the effect of XYKJP on inflammatory cytokines in colitis tissues and found that XYKJP treatment led to a reduction in the levels of IL-1β, TNF-α, and IL-6, and a significant improvement in the level of IL-10 and IL-22, as demonstrated by ELISA." (PMID 39133435, 2024). "Using in vivo and in vitro approaches with WT and conditional AhR KO mice under colitis conditions, AhR was shown to affect production of Muc2 after stimulation with an AhR ligand (I3C), and this appeared to be independent of IL-22." (PMID 38397081, 2024). "Mice lacking Npm1 in ILC3s exhibited decreased IL-22 production and accelerated development of colitis." (PMID 39103576, 2024).
colitis (continued). "Moreover, it escalates the production of IL-22 by ILC3s, thereby enhancing the integrity of the colonic mucosal barrier and facilitating mucosal repair in DSS-induced colitis." (PMID 39734222, 2024). "The intestinal epithelial target of IL-22 is MATH1+ cells, which regulate B3galt5 expression (mainly goblet cells) and induce epithelial regeneration (MATH1+ progenitor cells) to protect from the development of DSS colitis." (PMID 38733584, 2024). "For example, Rag1−/− or Il22−/−Rag1−/− mice received IL‐22‐deficient or wild‐type (WT) CD4+CD45RBhi T cells intraperitoneally, and although all mice developed colitis, the mice fully lacking IL‐22 developed most severe symptoms." (PMID 38363052, 2024). "Accumulating evidence has revealed that AhR can mitigate colitis by decreasing the serum inflammatory cytokines/chemokines (e.g., TNF‐α, IFN‐γ, MCP‐1, and IL‐17), enhancing the expression of IL‐10 and IL‐22, and strengthening the intestinal epithelial cell barrier." (PMID 38882491, 2024). "Interestingly, when we treated the infected colitis mice with LGG or BL, we observed a significant increase in IL-6, CXCL2, IL-1β, TNF-α, IL-17a, and IL-22 gene expression in the cecal tissue, indicating an enhanced inflammatory response." (PMID 38397855, 2024). "They additionally report that transfer of IL‐22 knockout (KO), but not IL‐17 KO T cells (CD4+CD45RBlo T and Treg depleted) to Rag1−/− mice reduced weight loss and colitis scores compared with mice who received WT T cells." (PMID 38363052, 2024). "B. fragilis may indirectly motivate ILC3 to secrete IL-22, followed by IL-22-induced STAT3 phosphorylation, hence promoting colonic mucosa regeneration in colitis." (PMID 37114045, 2023). "iNKT cells (particularly IL-9-producing iNKT cells) also up-regulate IL-22-producing ILC3s in the mLNs, ultimately preventing DSS-induced colitis under IFN-γ-dysregulated conditions, indicating that iNKT cells and ILC3s counter-regulate IFN-γ-mediated intestinal inflammation." (PMID 38274786, 2023). "However, previous research has shown that the TL1A/DR3 axis is protective in driving ILC3 IL-22 production and mucosal healing during DSS-induced colitis." (PMID 37122757, 2023). "Meanwhile, it has been suggested that IL-22 exhibited protective ability in regulation of gut inflammation by stimulating colon epithelial cell lines to produce IL-10 and SOCS3 to ameliorate DSS-induced colitis via upregulating claudin-2 expression." (PMID 36092152, 2022). "SCFAs, particularly butyrate, could enhance interleukin-22 (IL-22) production in CD4+T cells and ILCs to alleviate colitis in mice by activating GPR41 and inhibiting HDACs." (PMID 35565943, 2022). "In addition, in the presence of L-fucose, IL-22 and its related transcription factor AHR were significantly elevated in the colons of colitis mice." (PMID 36432480, 2022). "In colitis models, oral GDNPs 2 administration increased IEC survival and proliferation, decreased pro-inflammatory cytokines (TNF-α, IL-6, and IL-1), and increased anti-inflammatory cytokines (IL-10 and IL-22)." (PMID 36298592, 2022). "IL-10 inhibited IL-22 secretion by macrophages and T cells, and spontaneous colitis was prevented in mice lacking IL-10 and IL-22." (PMID 36012618, 2022). "Additionally, the expression of Il-22 (interleukin 22), Il-17f (interleukin 17f), and Rorγt (RAR-related orphan receptor gamma) were reduced in colitis mice." (PMID 35889745, 2022). "CTLA4 expression by Treg cells and IL22 and IL17 production by ILC3 innate lymphocytes have both been shown to prevent or limit the development of inflammatory bowel syndromes and particularly colitis in the LI." (PMID 35603158, 2022). "Using a novel humanized model of experimental colitis, we demonstrate that TNF interfered with the tissue repair program via induction of a soluble natural antagonist of IL-22 (IL-22Ra2; IL-22BP) in the colon and abrogated IL-22/STAT3-mediated mucosal repair during colitis." (PMID 35383266, 2022).